FHIP2B (FHF complex subunit HOOK interacting protein 2B)
Description:
Able to activate MAPK/ERK and TGFB signaling pathways. May regulate the activity of genes involved in intestinal barrier function and immunoprotective inflammation (By similarity). May play a role in cell proliferation.
Synonyms: FAM160B2; RAI16; FLJ21801; FAI16; RAM160B2
Tractability: PROTAC: ubiquitination databases record sites on it.
Gene: Protein-coding gene on chromosome 8 (22,089,139 to 22,104,911, forward strand). Ensembl gene ENSG00000158863.
Subcellular location (Human Protein Atlas): Nucleoplasm; Cytosol
Genetic constraint (gnomAD): Loss-of-function variants: 66 observed, 69.07 expected, observed/expected ratio (o/e) 0.96, 90% interval 0.78 to 1.17. The synonymous counts are far from expectation, so gnomAD's model fits this gene poorly and the ratio says little. Missense variants: 874 observed, 848.21 expected, observed/expected ratio (o/e) 1.03, 90% interval 0.97 to 1.09. Synonymous variants: 451 observed, 373.2 expected, observed/expected ratio (o/e) 1.21, 90% interval 1.12 to 1.31.
Homologues: Orthologues: chimpanzee FHIP2B (97% identical), macaque FHIP2B (97% identical), mouse Fhip2b (86% identical), guinea pig FHIP2B (86% identical), pig FHIP2B (85% identical), rat Fhip2b (85% identical), dog FHIP2B (85% identical), rabbit FHIP2B (84% identical), zebrafish fhip2b (49% identical), tropical clawed frog fhip2b (46% identical), Drosophila melanogaster CG3558 (19% identical), Caenorhabditis elegans C05D11.8 (14% identical). Paralogues in human: FHIP2A (52% identical), FHIP1B (22% identical), FHIP1A (21% identical).
Diseases named in the same sentence as FHIP2B in open-access papers:
FHIP2B is named in the same sentence as 6 diseases in open-access papers, as found by Europe PMC text mining. Sharing a sentence is not in itself a finding about the gene and the disease. The quoted sentences say what the papers report.
lymphoma (1 paper, 2023). A malignant (clonal) proliferation of B- lymphocytes or T- lymphocytes which involves the lymph nodes, bone marrow and/or extranodal sites. "However, the exact roles and specific functions of FHIP2B, POMT1, TTLL3, CROCC, and CD52 in lymphoma and the molecular mechanisms of their downmodulation upon MyD88L265P expression are not yet fully understood and require further research." (PMID 36982699, 2023).
FHIP2B also shares sentences with these, for which no sentence is quoted: hepatocellular carcinoma (2 papers); tumor (2); cancer (1); colitis (1); colon cancer (1).